TRBV29-1 (T cell receptor beta variable 29-1)
Description:
V region of the variable domain of T cell receptor (TR) beta chain that participates in the antigen recognition. Alpha-beta T cell receptors are antigen specific receptors which are essential to the immune response and are present on the cell surface of T lymphocytes. Recognize peptide-major histocompatibility (MH) (pMH) complexes that are displayed by antigen presenting cells (APC), a prerequisite for efficient T cell adaptive immunity against pathogens. Binding of alpha-beta TR to pMH complex initiates TR-CD3 clustering on the cell surface and intracellular activation of LCK that phosphorylates the ITAM motifs of CD3G, CD3D, CD3E and CD247 enabling the recruitment of ZAP70. In turn ZAP70 phosphorylates LAT, which recruits numerous signaling molecules to form the LAT signalosome. The LAT signalosome propagates signal branching to three major signaling pathways, the calcium, the mitogen-activated protein kinase (MAPK) kinase and the nuclear factor NF-kappa-B (NF-kB) pathways, leading to the mobilization of transcription factors that are critical for gene expression and essential for T cell growth and differentiation. The T cell repertoire is generated in the thymus, by V-(D)-J rearrangement. This repertoire is then shaped by intrathymic selection events to generate a peripheral T cell pool of self-MH restricted, non-autoaggressive T cells. Post-thymic interaction of alpha-beta TR with the pMH complexes shapes TR structural and functional avidity.
Synonyms: TCRBV4S1A1T; TRBV291; TCRBV29S1
Tractability: Antibody: UniProt places it where antibodies can reach, with medium confidence; UniProt predicts a signal peptide or a membrane-spanning region; its Gene Ontology location is reachable by antibodies, with medium confidence.
Gene: T-cell receptor variable (V) gene on chromosome 7 (142,740,206 to 142,740,894, forward strand). Ensembl gene ENSG00000232869.
Subcellular location: Cell membrane
Gene Ontology:
Biological process: cell surface receptor signaling pathway
Cellular component: plasma membrane
Homologues: Orthologues: macaque TRBV29-1 (94% identical), dog TRBV29-1 (75% identical), rabbit TRBV29-1 (74% identical), mouse Trbv30 (70% identical), rat Trbv30 (70% identical). Paralogues in human: TRBV20OR9-2 (62% identical), TRBV20-1 (59% identical), TRBV12-5 (26% identical), TRBV27 (26% identical), TRBV5-1 (26% identical), TRBV6-1 (26% identical), TRBV6-5 (26% identical), TRBV15 (25% identical), TRBV19 (25% identical), TRBV5-3 (25% identical), TRBV5-6 (25% identical), TRBV6-2 (25% identical), and 39 more.